Y_RNA (Y RNA )
Gene: Miscellaneous RNA gene on chromosome 1 (147,420,199 to 147,420,300, reverse strand). Ensembl gene ENSG00000207209.
Homologues: Orthologues: chimpanzee Y_RNA (98% identical), macaque Y_RNA (96% identical). Paralogues in human: Y_RNA (88% identical), RNY3 (87% identical), Y_RNA (87% identical), Y_RNA (86% identical), RNY3P1 (85% identical), Y_RNA (85% identical), RNY3P16 (84% identical), Y_RNA (84% identical), RNY3P4 (83% identical), Y_RNA (83% identical), RNY3P9 (82% identical), Y_RNA (82% identical), and 96 more.